LEP (leptin)
Diseases named in the same sentence as LEP in open-access papers (continued):
Sharing a sentence is not in itself a finding about the gene and the disease.
Obesity (continued). "Studies were included if they met the following criteria: (a) peer-reviewed, full-text articles, and (b) trials that included the impacts of IF plus Exe vs. Exe alone (control) on serum leptin and adiponectin in adults with or without overweight and obesity." (PMID 38933888, 2024). "For instance, while leptin may directly enhance cell migration, its impact could be modulated by other factors such as IL-6 or IGF-1, which are also upregulated in obesity." (PMID 39339753, 2024). "Leptin levels are significantly greater in obese OA patients than in non-obese OA patients, demonstrating that leptin mediates the relationship between OA and obesity." (PMID 39165638, 2024). "This was paralleled by a statistically increased expression of LEP mRNA levels in s.c. and Om AT biopsy, whereas the mRNA level of adiponectin was significantly decreased in the presence of obesity and IR (P < 0.05), irrespective of the AT depot analyzed." (PMID 38206766, 2024). "Obesity can inhibit the transport of leptin across the BBB, making it impossible for the brain to receive the “satiety signal” emitted by leptin, leading to overeating and worsening of obesity, which may lead to a series of metabolic diseases." (PMID 38678254, 2024). "Adipokines mainly involved in obesity and MetS are leptin, nonesterified free fatty acids, reactive oxygen species, adipocytic angiotensinogen, and resistin." (PMID 39411599, 2024). "Prior reports indicate that obesity does not affect the amount of leptin or IL-6 secreted from breast AT or purified breast adipocytes." (PMID 39408921, 2024). "Adiponectin is also expressed in airway epithelial cells; unlike leptin, adiponectin levels are decreased in patients with obesity and insulin resistance." (PMID 39272654, 2024). "Many individuals with obesity exhibit increased circulating concentrations of leptin without significant effect on energy balance." (PMID 39183855, 2024). "The relationship between obesity and OSA is further complicated by obesity-related hormones and cytokines, such as leptin, which may exacerbate respiratory instability during sleep." (PMID 39624686, 2024). "study about 111 children, asthma was more severe in the obese children with obesity with asthma than in the children without obesity and in the second group leptin and adiponectin levels were correlated with the asthma symptom score." (PMID 39371928, 2024). "Elevated leptin levels and the leptin-to-adiponectin ratio predict obesity gain in non-obese, prepubertal children." (PMID 38572009, 2024). "Moreover, obesity triggers the release of excessive inflammatory cytokines like tumor necrosis factor ɑ (TNF-ɑ) and leptin from adipose tissue, further aggravating glomerular injury." (PMID 38451930, 2024). "As expected, the absence of obesity in SADI-S rats was also indicated by the reduced plasma leptin levels compared to sham-operated and SG animals (p < 0.001 for all)." (PMID 37935948, 2024). "Additionally, upregulation of FTO/CX3CL1 and suppressor of cytokine signaling 3 (SOCS3) in the hypothalamus impairs leptin- and signal transducer and activator of transcription 3 (STAT3) signaling, resulting in leptin resistance and obesity." (PMID 39125332, 2024). "In addition to obesity, MSG-obese mice with pre-diabetes, leptin and insulin resistance exhibited central insulin resistance leading to increased hippocampal Tau hyperphosphorylation." (PMID 38577975, 2024). "Extreme fEAA was observed in both leptin (LEP) and the melanocortin receptor proteins (MC1R-MC5R) –components of an established hypothalamic signalling pathway that responds to increased levels of adiposity/obesity by promoting satiety." (PMID 39401228, 2024). "Obesity-induced epithelial remodeling may involve various factors, including HMGB1, the role of leptin, CysLTs, ORMDL3, matrikines like PGP, and cytokines such as IL-4 and IFN-γ, which may contribute to epithelial alterations." (PMID 38562155, 2024).
Obesity (continued). "Nonetheless, excessive leptin secretion did not suppress appetite and induced obesity in BDNF heterozygous mice." (PMID 38672461, 2024). "This suggests that leptin resistance in the presence of high leptin levels leads to a lack of action of this molecule, which favors the development of insulin resistance and obesity." (PMID 39683415, 2024). "SBP had positive correlations with obesity parameters, leptin, insulin, and insulin resistance but had a negative correlation with insulin sensitivity." (PMID 39285220, 2024). "However, treatments aimed at reducing elevated leptin levels, such as Metreleptin, leptin-sensitising medications, soluble leptin receptors, and leptin receptor antagonists, may complement efforts to raise adiponectin levels in the treatment of obesity-related diseases." (PMID 38339282, 2024). "For instance, as happens in obesity, GDM is followed by lower adiponectin and higher leptin levels." (PMID 39083072, 2024). "Leptin, adiponectin, and ghrelin are thought to impact asthma development and control, regardless of obesity or gender." (PMID 39407941, 2024). "This study addresses the gap in understanding the relationships between dietary fat types, inflammation markers, and leptin levels in individuals with obesity, particularly in non-Western populations." (PMID 39700087, 2024). "In obesity, there is development of leptin resistance, where high leptin levels no longer effectively signal satiety, resulting in chronic hyperleptinemia." (PMID 39682585, 2024). "In fact, several animal models of obesity and HFD have also demonstrated that certain HDAC inhibitors can effectively reduce adiposity, improve leptin sensitivity, increase energy expenditure, and improve insulin sensitivity and glucose homeostasis in obese animals." (PMID 39109269, 2024). "In addition, resistin correlated positively with indices of obesity, such as BMI, BMI z-score, TMI, HC, WHtR and leptin, while changes in resistin concentrations correlated positively with WC, WC z score, WHtR, muscle mass percentage and fat-free mass." (PMID 39519480, 2024). "In obesity, the SNS-stimulating action of leptin depends on a functional AngII type 1a receptor (AT1aR), which tonically suppresses inhibitory neuropeptide Y (NPY) input to POMC neurons within the ArcN and/or the presympathetic neurons in the periventricular nucleus." (PMID 38186879, 2024). "Based on these data, we propose that, during obesity, reduced AT-EOS content is accompanied by decreased IL-4 levels, and this adversely affects adipocyte leptin secretion, thereby contributing to development of hyperleptinemia and leptin resistance." (PMID 38206766, 2024). "Although the function of BMP7 in energy metabolism is not well characterized, it seems to act through leptin-independent mechanisms, making it of therapeutic interest in obesity, since the obese state is often characterized by leptin resistance." (PMID 39033139, 2024). "Lack of appropriate leptin signaling manifests in an intense drive to eat (hyperphagia), impaired satiety, and severe early-onset obesity." (PMID 38470203, 2024). "The anorexigenic adipokine leptin present higher levels in non-pregnant individuals with obesity, which further contributes to leptin resistance characterized by the reduction of satiety and catabolic metabolism, leading to weight gain." (PMID 39083072, 2024). "For example, a study in rats with ME1 deficiency found that ME1 may promote adiposity and hepatic steatosis and induce circulating insulin and leptin, supporting the therapeutic targeting of ME1 for obesity, diabetes, and hepatic steatosis." (PMID 38836220, 2024). "Mice lacking either leptin (ob/ob mice) or the leptin receptor (db/db) are hyperphagic and develop severe obesity, insulin resistance, hyperlipidemia and hepatic steatosis, but rarely develop steatohepatitis without additional stimuli (HFD, MCD, etc.)." (PMID 38672461, 2024).
Obesity (continued). "Unlike adipokines such as leptin, plasma adiponectin levels are negatively associated with adiposity and decreased in T2DM, obesity, and insulin resistance." (PMID 39125659, 2024). "By improving leptin sensitivity and correcting signaling pathways involved in appetite regulation and energy homeostasis, PEA may help reduce obesity-related complications and improve metabolic health." (PMID 39770936, 2024). "This has led to the development of a polygenic rat model that exhibits adult-onset obesity, insulin resistance and type 2 DM without the need for dietary intervention while maintaining leptin signaling." (PMID 38339160, 2024). "These human data indicate that obesity-related hyperleptinemia is associated with a decline in TET2 expression in adipocytes, supporting a negative feedback loop between TET2 and leptin in the context of obesity." (PMID 38561362, 2024). "While leptin generally promotes testosterone synthesis, in obesity, high leptin levels do not lead to increased testosterone due to leptin resistance and dysregulated signaling." (PMID 39840189, 2024). "Leptin is a 167-amino-acid hormone discovered by Douglas Coleman and Jeffrey Friedman in 1994, first known as the obesity hormone; it is synthesized predominantly (but not entirely) by white adipose tissue." (PMID 39125635, 2024). "The present systematic review and meta-analysis was conducted to examine the effects of combining IF diets with Exe as compared with Exe alone, on circulating leptin and adiponectin levels in humans with or without obesity and obesity-related diseases." (PMID 38933888, 2024). "The levels of determined hormones in the adipose tissue of animals from the palatable + KSK-94 group, such as leptin and resistin, after treatment, were at a comparable level as in the adipose tissue collected from the control group without obesity." (PMID 39065709, 2024). "Even if the underlying mechanisms of this association have not been elucidated yet, some authors have reported significantly higher leptin levels in RTT patients than in controls, but this finding was not always associated with obesity." (PMID 38540345, 2024). "In our study, gut microbiota recipient mice from obese donors do not show any leptin or insulin elevation typical from obesity." (PMID 37106463, 2023). "Paralleling this remodeling of adipose tissue, we found that leptin, resistin, glucagon-like peptide-1 (GLP-1), glucagon, TNF-α, and IL-6 were elevated in serum from DIO-HFD mice relative to CON-LFD, and DIO-VSG suppressed this obesity-driven increase." (PMID 37698918, 2023). "Leptin and FABP4 were highly expressed in WAT as obesity genes." (PMID 37073893, 2023). "Aerobic exercise decreases leptin levels in PVAT, improves leptin resistance, alleviates hypoxia and macrophage infiltration, and prevents infiltration of immune cells into PVAT, which further prevents vascular dysfunction in age-induced obesity." (PMID 37089434, 2023). "In healthy individuals, leptin works through the hypothalamus to reduce hunger, but in obesity, leptin resistance is not uncommon." (PMID 36766750, 2023). "On the other hand, loss of LepR in POMC/CART, but not AgRP/NPY, neurons in the adult mice promotes obesity only when fed HFD These results suggest that the primary target of leptin is context-dependent." (PMID 37547309, 2023). "Overall, these data suggest that high circulating levels of insulin (and/or other adiposity hormones, like leptin) in obesity can lead to striatal InsR insensitivity, independent of the caloric source used to induce obesity." (PMID 36979453, 2023). "Leptin, a well-known adipose-derived anorexigenic hormone whose circulating levels are reflective of adipose tissue expansion and contraction, was decreased with ABA and notably increased in obesity." (PMID 37582711, 2023). "The main goal of our study was to determine whether IN leptin is effective for OIRD treatment in opioid-tolerant subjects of both sexes in the absence and presence of obesity." (PMID 38162827, 2023).
Obesity (continued). "When the hypothalamus does not respond normally to these leptin signals (i.e., leptin resistance), this results in obesity." (PMID 38001759, 2023). "Following the concepts above, the prediction would be that the absence of UCP1 in itself should lead to overt obesity, similarly to the obesity-inducing effect of the absence of leptin in the ob/ob mouse." (PMID 37661736, 2023). "The authors determined the level of expression of LEP in PCOS patients with or without obesity and in GCs treated with insulin." (PMID 37562217, 2023). "Apart from obesity increasing insulin, IGF-1, leptin, IL-6, TNF-α and decreasing levels of adiponectin which activates the PI3K-AKT signalling pathway in CRC, high BMI inhibits methylation of PI3K-AKT signalling pathway genes, constitutively activating the pathway." (PMID 37233716, 2023). "Pemt–/– mice do not develop obesity with high-fat feeding, retain insulin sensitivity, and have lower leptin concentrations compared with littermate controls." (PMID 36472923, 2023). "Disruption of leptin-CRP and the interaction between CRP and leptin receptors may be a target for the treatment of obesity and obesity-related NAFLD." (PMID 37893085, 2023). "Leptin resistance is defined as leptin’s inability to exert its anorexigenic effects in obese persons, and therefore leptin’s lack of therapeutic usefulness in obesity." (PMID 36790719, 2023). "This review drew that probiotics might act as a role in regulating HDL-C, LDL-C, adiponectin, leptin and TNF-α in overweight or obesity children." (PMID 37542325, 2023). "While leptin levels tend to increase with OSA severity, this association is likely confounded by obesity rather than OSA itself." (PMID 37834123, 2023). "Adipokines such as leptin, adiponectin, interleukin (IL) 6, tumour necrosis factor‐alpha (TNF‐α) and plasminogen activator inhibitor (PAI‐1) from adipose tissue, are the main determinants of obesity‐induced inflammation." (PMID 37275420, 2023). "In murine models lacking leptin, notable observations include hyperphagia, obesity, and insulin resistance, highlighting the essential role of leptin in appetite regulation, energy balance, and insulin sensitivity." (PMID 38138996, 2023). "Unlike leptin, preclinical models support a more significant role for the adipokine lipocalin-2 (Lcn2) in obesity-driven PDAC." (PMID 37648285, 2023). "This suggests that obesity is often characterized by leptin resistance rather than a defect in the obesity gene itself." (PMID 37593311, 2023). "The approach to the relationship between EMS and obesity is constantly evolving because of the significant dysfunction of adipocyte tissue (both perirenal and retroperitoneal) in EMS horses (adipocyte hyperplasia; overexpression of leptin and cytokines)." (PMID 37628596, 2023). "In support of this view, while obesity has been shown to increase LepR expression in the ArcN, the administration of leptin to further increase plasma levels in obese mice failed to induce additional LepR expression, unlike in lean mice." (PMID 36769012, 2023). "For example, curcumin prevents obesity-related colorectal cancer by attenuating chronic inflammation and improving adipokine imbalance, reducing cyclooxygenase-2 (COX-2), AMPK, NF-κB, TNFα, IL-6 and leptin levels, while increasing adiponectin levels." (PMID 36670988, 2023). "However, in ob/ob mice, which exhibit obesity due to the inactivation mutation of the leptin gene, metformin may not exert its leptin-sensitizing effects through promoting leptin receptor expression, resulting in minimal or negligible effects on body weight regulation." (PMID 37860765, 2023). "In addition, the model of sucrose-diet induced obesity is characterized by increased plasma free fatty acid (FFA) levels, hypertriglyceridemia (TG) and hyperleptinemia, and is expected to develop leptin resistance." (PMID 36978976, 2023).
Obesity (continued). "ZDSD rats are susceptible to high fat (HF) diet-induced obesity and T2D, but unlike ZDF rats, ZDSD rats have preserved the critical leptin signaling pathway." (PMID 37233701, 2023). "Future research should explore the potential mechanisms of diet induced leptin resistance in the absence of obesity (but in the presence of AgRP neuronal hyperexcitability)." (PMID 36725979, 2023). "During obesity, hypertrophic adipocytes release proinflammatory adipokines and cytokines, such as leptin, visfatin, resistin, MCP-1 and IL-6, which contribute not only to local but also systemic and liver inflammation." (PMID 37189422, 2023). "Obesity, which is common in people with T2DM, is highly correlated with greater BMD, most likely due to mechanical loading and hormonal factors such as insulin, estrogen, and leptin, as well as other hormonal factors." (PMID 37885541, 2023). "Its deletion provokes metabolic disorders in SH2B1 KO mice, including leptin resistance, obesity, and glucose intolerance whereas restoration of SH2B1 corrected these metabolic disturbances and improved JAK2-mediated leptin signaling and regulation of hypothalamic orexigenic neuropeptides." (PMID 36674935, 2023). "The aim of this study was to explore whether plasma levels of leptin in pre- and post-pubertal children with ASD and/or overweightness/obesity differ from those of BMI- and age-matched healthy controls." (PMID 36902307, 2023). "The lack of effect by leptin treatment in common obesity has been called leptin resistance and is not fully understood, although a number of possible mechanisms have been suggested." (PMID 37661748, 2023). "Unfortunately, it seems that systemic leptin treatment per se is not very effective in treating common obesity." (PMID 37661748, 2023). "Besides, other researchers also found that, due to obesity in PCOS patients, the increased circulating leptin (LP) levels within the body led to leptin resistance, which can also significantly promote chronic low-grade inflammation." (PMID 36817281, 2023). "Taken together, our results allow us to conclude that the weight loss promoted by BS in female patients with severe obesity presenting or not presenting with MetS could remarkably improve anthropometric, biochemical, and systemic inflammatory variables, especially the ratio of adiponectin to leptin." (PMID 37571250, 2023). "Second, visceral fat is also an active endocrine tissue, increased secretion of adipose-specific cytokines (e.g., leptin, IL-6, and TNF-α) in patients with obesity or abnormal adipose distribution also inhibits gonadotropin secretion, which in turn inhibits HPG axis." (PMID 38260153, 2023). "According to studies, the FTO gene was related to obesity and certain types of malignancies, including CRC, by altering the impacts of leptin and adiponectin on colorectal carcinogenesis or participating in adipogenesis and tumorigenesis through the mammalian target protein rapamycin (mTOR)." (PMID 37543622, 2023). "In turn, obesity development was attenuated in CerS6ΔSF-1 female mice, as evidenced by reduced weight gain and body fat content, weights of gWAT and subcutaneous WAT (sWAT) depots, and circulating leptin levels compared to their controls." (PMID 38016943, 2023). "Our study demonstrated that regardless of obesity, serum leptin SR level was significantly higher in patients with T2DM compared to healthy subjects." (PMID 36950695, 2023). "The effect of leptin without obesity was modeled in female F344BN F1 hybrid rats by systemically administering recombinant rat leptin versus saline for 23 weeks via osmotic pumps." (PMID 37457883, 2023). "Likewise, a three-month voluntary training was capable to partially restore leptin-induced STAT3 phosphorylation in HFD-fed mice, suggesting that exercise improves central leptin signaling in obesity." (PMID 36829858, 2023).